GIMAP1-GIMAP5 (GIMAP1-GIMAP5 readthrough)
Gene: Protein-coding gene on chromosome 7 (150,716,668 to 150,743,646, forward strand). Ensembl gene ENSG00000281887.
Genetic constraint (gnomAD): Loss-of-function variants: 20 observed, 30.91 expected, observed/expected ratio (o/e) 0.65, 90% interval 0.45 to 0.94. The upper end of that interval is the gene's LOEUF score, 0.94, which puts it in group 3 of 6, group 1 being the genes least tolerant of losing a copy. Missense variants: 611 observed, 660.55 expected, observed/expected ratio (o/e) 0.92, 90% interval 0.87 to 0.99. Synonymous variants: 287 observed, 273.66 expected, observed/expected ratio (o/e) 1.05, 90% interval 0.95 to 1.16.